DGCR8 (DGCR8 microprocessor complex subunit)
Diseases named in the same sentence as DGCR8 in open-access papers (continued):
Sharing a sentence is not in itself a finding about the gene and the disease.
ovarian carcinoma (8 papers, 2012 to 2025). A malignant neoplasm originating from the surface ovarian epithelium. "It has been reported that silencing of DGCR8 can decrease the level of miR-27b in ovarian cancer and therefore suppress cancer progression." (PMID 34389030, 2021). "Knockdown of DGCR8 in ovarian cancer cells disturbs their proliferation, migration, and invasion and increases their sensitivity to the chemotherapeutic drug cisplatin, which suggests that an elevated level of DGCR8 is associated with carcinogenesis." (PMID 24904827, 2014). "Mediated by miR-27b, DGCR8 functions as oncogene in Ovarian cancer." (PMID 35057823, 2022). "Indeed, the expression levels of Drosha and Dicer are down-regulated in ovarian cancer (Kobel, Gilks & Huntsman, 2009) and neuroblastomas, while DGCR8 is up-regulated in esophageal cancer, bladder cancer, and prostate cancer." (PMID 27957388, 2016). "DGCR8 expression levels are over-expressed in basal cell carcinoma, SCC, colorectal cancer (CRC), gastrointestinal cancer, and ovarian cancer." (PMID 24904827, 2014).
thyroid (8 papers, 2016 to 2026). "We trace the molecular trajectories from benignity to malignancy in DICER1- and DGCR8-mutated thyroid lesions using multiomic profiling on over 30 DICER1-/DGCR8-mutated samples." (PMID 41657311, 2026). "Recent findings have expanded our understanding of DICER1 syndrome and DGCR8-related thyroid disorders, revealing a broader spectrum of thyroid lesions associated with mutations in these genes than previously recognised." (PMID 41104964, 2025). "This review examines the emerging roles of DICER1 and DGCR8, key components of the miRNA biogenesis pathway, in thyroid pathogenesis, with a particular focus on their association with oncocytic morphology." (PMID 41104964, 2025). "In a similar way,the identification of DICER1 and DGCR8 mutationsunderlying DICER1 and FMGS syndromes, respectively, paved the way for extendedanalyses of DICER1 and DGCR8 mutations in somatictissues from patients with thyroid disease." (PMID 39601261, 2024). "These mutations were associated with reduced DGCR8 mRNA levels and a distinct miRNA profile, suggesting their role in thyroid carcinogenesis." (PMID 39061714, 2024). "Succeeding DICER1 alterations in the susceptibility of thyroid disease, we reaffirm DGCR8 as another important player of the miRNA microprocessor complex team." (PMID 36499151, 2022). "The obtained data solidify DGCR8 as another important player of miRNA-related gene mutations in thyroid tumorigenesis, particularly in follicular-patterned thyroid tumours." (PMID 36499151, 2022). "In this study, our aim was to characterize DGCR8 microprocessor subunit in a series of thyroid lesions by genotyping DGCR8 recurrent mutation p.(E518K), to evaluate DGCR8 mRNA and protein expression by real-time PCR (qPCR) and immunohistochemistry (IHC), respectively." (PMID 36499151, 2022). "In this study, these observations were particular evident in follicular-patterned carcinomas, suggesting that not only mutations but also alterations in DGCR8 mRNA/protein expression may be important in thyroid tumorigenesis." (PMID 36499151, 2022). "The scope of this review extends beyond DICER1 to include DGCR8 and the broader miRNA maturation axis, acknowledging their potential involvement in thyroid tumorigenesis." (PMID 41104964, 2025). "For DGCR8, the focus has been even more limited, though its molecular role in thyroid tumorigenesis is gaining attention." (PMID 41104964, 2025). "Beyond DGCR8, somatic DICER1 mutations are reported in follicular-patterned lesions of thyroid (benign and malignant) which underlines the importance of the miRNA processing genes in follicular-patterned lesions." (PMID 36499151, 2022). "DGCR8 emerged recently as miRNAs biogenesis pathway protein with a highlighted role in thyroid disease." (PMID 36499151, 2022). "Here we show that knockout of Dgcr8 leads to a similar phenotype of severe hypothyroidism due to thyroid hypoplasia confirming the importance of miRNAs for thyroid development and maintenance." (PMID 27090781, 2016). "Although DICER has been more extensively studied, emerging research suggests that another key player in miRNA biogenesis, DGCR8, may also contribute to thyroid tumorigenesis." (PMID 41104964, 2025). "This opens new questions about other miRNA biogenesis genes, besides DICER1 and DGCR8, which may have a role in thyroid tumorigenesis." (PMID 38607000, 2024). "In addition,DICER1 and DGCR8 mutants in thyroid tumorsshare a similar miRNA expression profile, distinguishing them fromDICER1/DGCR8 wild-type tumors." (PMID 39601261, 2024). "Of note, only one of the schwannomatosis patients in our cohort had a thyroid related comorbidity, which was not classified as familial and no DGCR8 variant was identified in this patient." (PMID 35723634, 2022).
Infertility (7 papers, 2014 to 2025). "DGCR8 is involved in miRNA biogenesis; a loss of DGCR8 in C. elegans leads to a failure to ovulate and infertility." (PMID 37685885, 2023). "Of these, DROSHA, a target gene, is an RNase III enzyme and a cofactor of DGCR8 in the nucleus that mediates the processing of miRNA primary transcript in spermatozoa, and impaired expression caused deficiency in miRNA synthesis and infertility." (PMID 40141332, 2025). "The phenotypes of Dgcr8, Drosha and Dicer germline cKOs are largely congruent, and include infertility (or subfertility), decreased sperm count and disrupted sperm morphology." (PMID 27578177, 2016). "Previous studies investigating conditional knock-outs of Dgcr8, Drosha and Dicer in the male germ line have noted many of the same gross morphological defects we observed, including infertility (or subfertility), decreased sperm count, and disrupted sperm morphology." (PMID 25934699, 2015). "Interestingly, the ablation of either Dicer1 or Dgcr8 in the germ cell lineage using the Ddx4:Cre transgene led to complete infertility." (PMID 25244517, 2014).
thyroid cancer (6 papers, 2021 to 2026). "Transcriptomic analyses revealed mutation-specific effects on the microenvironment, whereby DICER1 mutations activated canonical thyroid cancer progression pathways, whereas altered DGCR8 associated with immune-related changes." (PMID 41657311, 2026). "We present for the first time the p.(E518K) mutation in a case of poorly differentiated thyroid carcinoma and present the deregulation of DGCR8 expression at mRNA level in follicular-patterned tumours." (PMID 36499151, 2022). "Similarly, a recurrent somaticmutation of the DGCR8 gene has been observed in highlyaggressive FTCs and in some indolent cases of encapsulated follicular variant ofpapillary thyroid carcinoma." (PMID 39601261, 2024). "As this is the first study evaluating protein expression, further studies will help to clarify the mRNA and protein expression of DGCR8 in thyroid carcinomas." (PMID 36499151, 2022). "With the recent description of a DGCR8 mutation (also located in 22q) in familial-MNG forms and sporadic thyroid carcinomas, we set to evaluate DGCR8 as candidate gene in thyroid lesions." (PMID 36499151, 2022). "DGCR8 mutational carriers, on the other hand, often present with FND, whereas the true incidence of thyroid cancer within this syndrome is unknown." (PMID 38252873, 2024). "Moreover, the majority ofFTCs in Paulsson’s cohort exhibited downregulation of DGCR8mRNA, further establishing DGCR8 as a potential tumor suppressorgene in thyroid cancer." (PMID 39601261, 2024).
lung carcinoma (5 papers, 2015 to 2024). "Conversely, down-regulation of DGCR8 enhances cellular transformation and tumor growth in lung cancer." (PMID 26308063, 2015). "Down-regulation of DGCR8 enhances cellular transformation and tumor gurowth in lung cancer." (PMID 26308063, 2015).
thyroid tumor (5 papers, 2019 to 2025). A benign or malignant neoplasm affecting the thyroid gland. "Mutations in micro-RNA (miRNA) regulators DICER1 and DGCR8 have recently been uncovered, revealing a potential novel mechanism driving thyroid tumor development." (PMID 38252873, 2024). "Future investigations of dysregulated miRNAs in DICER1 and DGCR8 mutated tumors may provide important clues for thyroid tumor initiation and progression." (PMID 38252873, 2024). "Future studies employing dedicated mitochondrial functional assays will be crucial to assess the metabolic consequences of DICER1- and DGCR8-related miRNA biogenesis disruption in thyroid tumours." (PMID 41104964, 2025). "The mutational status in the hot spot regions of DICER1, DROSHA, TARBP2, DGCR8 and the most commonly affected genes in thyroid tumors was investigated on both tumor and paired normal tissues." (PMID 30956758, 2019).
prostate carcinoma (4 papers, 2020 to 2023). A carcinoma that arises from epithelial cells of the prostate gland. "Co-immunoprecipitation identified the interaction between HNRNPA2B1 and DGCR8 in prostate cancer cells." (PMID 37215455, 2023). "CircPSMC3 inhibits prostate cancer cell proliferation by downregulating DGCR8." (PMID 35945192, 2022). "Later studies found that circPSMC3 inhibited cell proliferation of nasopharyngeal carcinoma and prostate cancer by down‐regulating ROCK1 and DGCR8, respectively." (PMID 32808450, 2020).
schwannomatosis (4 papers, 2022 to 2025). The least frequent form of the rare genetic disorder neurofibromatosis. "Regarding the DGCR8 gene, the specific E518K variant causes multinodular goiter with schwannomatosis, and somatic loss of heterozygosity has been shown as a second event in tumor tissues from these patients." (PMID 38252873, 2024). "Following DICER1-syndrome, another syndrome caused by impaired miRNA biogenesis was recently described: a syndrome characterized by familial follicular nodular disease and schwannomatosis caused by a germline mutation in DGCR8, the E518K mutation." (PMID 38607000, 2024). "In contrast to DGCR8, evidence supporting the involvement of variants in CDKN2A and COQ6 in schwannomatosis pathogenesis is less conclusive." (PMID 35723634, 2022). "More recently, a study identified a germline variant in exon 7 of DGCR8 (NM_022720.6:c.1552G>A; p.Glu518Lys) in all affected members of a family with both euthyroid multinodular goiter (MNG) and schwannomatosis." (PMID 35723634, 2022). "Screening of the coding region of DGCR8, COQ6, CDKN2A, and CDKN2B was carried out, based on previous reports that point to these genes as potential candidate genes for schwannomatosis." (PMID 35723634, 2022). "Other proposed candidate genes for schwannomatosis include the coenzyme Q6, monooxygenase (COQ6) gene, and DGCR8 microprocessor complex subunit (DGCR8)." (PMID 35723634, 2022).
cervical cancer (3 papers, 2013 to 2018). A primary or metastatic malignant neoplasm involving the cervix. "HPV16 E7 also promotes miR-27b expression in cervical cancer cell lines by increasing DiGeorge syndrome critical region gene 8 (DGCR8), which in turn decreases the expression of miR-27b target polo like kinase 2 (PLK2) and promotes proliferation and invasion." (PMID 30563114, 2018). "This is an indication whether HPV16 E7 up-regulates miR-27b is mediated by DGCR8 in cervical cancer." (PMID 26910911, 2016). "MiR-27b was proved to be up-regulated by HPV16 E7 through DGCR8 to promote proliferation and suppresses apoptosis by targeting PLK2 in cervical cancer cells." (PMID 26910911, 2016). "The fact that miR-27b is up-regulated by virus oncogene E7 through DGCR8, negatively regulates PLK2 in HPV16 positive cervical cancer cells suggests that miR-27b is likely to play an oncogenic role in cervical cancer to promote cell proliferation and inhibit paclitaxel-induced cell apoptosis." (PMID 26910911, 2016).
cognitive deficits (3 papers, 2011 to 2025). "Dgcr8 haploinsufficient mice (Dgcr8+/-) have reduced expression of microRNAs in brain and display cognitive deficits, but how microRNA deficiency affects the development and function of neurons in the cerebral cortex is not fully understood." (PMID 21466685, 2011). "Dgcr8 haploinsufficient mice (Dgcr8 ±) displayed reduced expression of miRNAs in the brain and showed cognitive deficits, along with altered electrical properties of layer 5 pyramidal neurons in the mPFC, decreased complexity of basal dendrites, and reduced excitatory synaptic transmission." (PMID 37213213, 2023).
colon cancer (3 papers, 2020 to 2024). "Regarding DGCR8 in 293T, we could detect a lower-molecular-weight isoform enriched in CM reported previously to be differentially expressed across colon cancer cell lines, pointing to another example of release or stabilization of RBP isoforms in the extracellular space." (PMID 37228754, 2023). "That said, whereas the expressions of the majority of appreciably expressed miRNAs in HCT116 colon cancer cells are significantly decreased in individual knockouts (KOs) of DROSHA, DGCR8, XPO5, and DICER, on average, only 3.5% of tsRNA, ysRNA, and rsRNA expressions are impaired." (PMID 39634108, 2024).
colorectal cancer (3 papers, 2012 to 2015). A primary or metastatic malignant neoplasm that affects the colon or rectum. "In colorectal cancer, DGCR8 expression is increased in tumors compared with normal tissue." (PMID 26308063, 2015).
depression (3 papers, 2019 to 2024). "It is likely that the dysregulation of Dgcr8 could give rise to the depression phenotype and the underlying mechanism needs more refined work to uncover." (PMID 35492695, 2022). "This is associated with a variety of diseases, including depression, and can alter an individual’s susceptibility to the disease; for examples microRNA processing genes DGCR8 rs3757 and AGO1 rs636832 are significantly associated with depression." (PMID 38711022, 2024).
dilated cardiomyopathy (3 papers, 2010 to 2020). Cardiomyopathy which is characterized by dilation and contractile dysfunction of the left and right ventricles. "In mice, cardiomyocyte-specific deletion of Dgcr8 induces cardiac fibrosis with left ventricular malfunction progressing to a dilated cardiomyopathy and premature lethality." (PMID 30854230, 2019). "A recent study found that deletion of DGCR8 in cardiomyocytes leads to left ventricular malfunction progressing to a dilated cardiomyopathy and premature lethality, which suggests a central role of this gene in cardiovascular function." (PMID 20211803, 2010).
melanoma (3 papers, 2014 to 2024). A malignant, usually aggressive tumor composed of atypical, neoplastic melanocytes. "For example, ADAR1 can also form a heterodimeric complex with DGCR8 and possibly impede Drosha-DGCR8 complex formation, hence altering miRNA expression profiles in melanoma." (PMID 38689093, 2024). "Other than MTAP and SEPTIN5, CDKN2A, CDKN2B, HIRA, and DGCR8 were the only recurrently altered cutaneous melanoma genes that were not recurrently altered in acral or mucosal melanomas, which frequently lack the presence of UV-induced mutations." (PMID 38758740, 2024). "Additionally, DGCR8 and AGO2 mRNA expression levels analysis did not even show any significant differences between malignant melanomas (primary cutaneous malignant melanoma and cutaneous malignant melanoma metastases) and benign melanocytic nevi." (PMID 23775303, 2014).
neuroblastoma (3 papers, 2012 to 2014). Neuroblastoma (NB) is the most common solid, extracranial childhood tumor. "Because the novel miRNA candidates had strong representation in human brain, we repeated the experiment in differentiated SH-SY5Y neuroblastoma cells, knocking down Dicer, Drosha, Argonaute 2 (Ago2) or DGCR8." (PMID 24708865, 2014).
pineoblastoma (3 papers, 2020 to 2024). Pineoblastoma is a rare, malignant type of supratentorial primitive neuroectodermal tumor (sPNET), found mainly in children (less than 10% of cases are reported in adults), and located in the pineal region of the brain but that can metastasize along the neuroaxis. "Moreover, somatic DROSHA and DGCR8 mutations, both related to the Dicer miRNA-regulating pathway, have been recently documented in pineoblastomas, in addition to germline and somatic DICER1 mutations, indicating that pineoblastoma development is influenced by disturbances of miRNA processes." (PMID 33552988, 2020).
renal failure (3 papers, 2015 to 2022). "Collecting duct-specific inactivation of Dicer and other critical miRNA biogenesis-associated genes (including Dgcr8, Ago1, 2, 3, and 4) causes renal failure in adult mice because of progressive tubulointerstitial fibrosis and interstitial inflammation." (PMID 35531954, 2022). "Likewise, ablation of either Dicer or Dgcr8 from distal nephron and ureteric bud derivatives, respectively, results in renal abnormalities and kidney failure, which are ultimately associated with downregulation of miR-200 family members." (PMID 35531954, 2022). "Pax8Cre-mediated conditional loss of DiGeorge syndrome critical region 8 (Dgcr8), an essential component of the nuclear machinery that is required for microRNA biogenesis, resulted in severe hypothyroidism, massively reduced body weight and ultimately led to renal failure and death of the animals." (PMID 27090781, 2016). "Animals with a gene deletion of Dgcr8 in these tissues developed severe hydronephrosis, kidney cysts, progressive renal failure and premature death within the first two months after birth, a phenotype strongly resembling Dicer deletion." (PMID 25881298, 2015). "Here we show that conditional gene deletion of the essential miRNA-processing enzyme Dgcr8 in the developing renal tubular system results in severe developmental defects and kidney failure." (PMID 25881298, 2015).
Autoimmunity (2 papers, 2015 to 2016). The occurrence of an immune reaction against the organism's own cells or tissues. "The lack of Dicer or DGCR8 causes premature thymic involution and diminished T-cell output and contributes to the development of autoimmunity." (PMID 27933063, 2016). "In fact, in mice where TEC do not produce miRNA due conditionally inactivate Dgcr8 gene, there is a specific loss of mature mTEChi and AIRE+ subsets that induce a breakdown in thymic central tolerance with the presence of autoantibodies or development of spontaneous autoimmunity." (PMID 26347748, 2015).
breast tumors (2 papers, 2015 to 2021). "We found that these genes were deregulated in ER+ compared to ER− breast tumors: DICER1, DROSHA and DGCR8 were significantly under-expressed in ER− while AGO2 was moderate over-expressed in ER−." (PMID 26141719, 2015).
cardiac hypertrophy (2 papers, 2019 to 2025). "In view of these results, DGCR8 decrease appears as a potential origin for the cardiac fibrosis and hypertrophy driven by maternal exposure to high-fat diet." (PMID 30854230, 2019). "Our data highlighted a new potential pathway through which DGCR8 alterations could lead to cardiac hypertrophy and fibrosis involving at least in part TGFβ pathway." (PMID 30854230, 2019).